MUC1 (mucin 1, cell surface associated)
Diseases named in the same sentence as MUC1 in open-access papers (continued):
Sharing a sentence is not in itself a finding about the gene and the disease.
breast carcinoma (continued). "Consistent with this; one study showed that MUC1 promoter had NF-κB binding sites that involved in the cytokines-induced MUC1 expression in breast cancer cells." (PMID 27830724, 2016). "Pro-inflammatory cytokines TNF-α and IFN-γ also enhanced the expression of MUC1 in breast cancer cells through NF-κB and signal transducer and activator of transcription 1 (STAT1) activation, respectively." (PMID 27754373, 2016). "In contrast, many breast cancers express MUC1-TM at high levels and of these, a discrete subset shows high MUC1-ARF expression." (PMID 27768738, 2016). "Such natural antibodies directed against MUC1 glycopeptides can be detected in the serum of breast cancer patients." (PMID 27153100, 2016). "The protein that carries T antigen depends on the tumor type, and includes several mucins and mucin-type proteins, such as CD44 on colorectal cancer, MUC1 on breast cancer, and CD164 in gastric and prostate cancer." (PMID 27153100, 2016). "The basic properties of the Apt-Td complex and its efficacy as a targeted drug delivery system were evaluated in vitro, using the MUC1-expressing MCF-7 breast cancer cell line as the model system." (PMID 27203221, 2016). "We here report that Apt-Td delivers doxorubicin to MUC1-positive breast cancer cells in a targeted manner." (PMID 27203221, 2016). "The accepted consensus is that this increased expression in breast cancer cells in some way links MUC1-TM protein to a malignant phenotype [see review]." (PMID 27768738, 2016). "Whilst CA 27.29 is a soluble form of the MUC-1 glycoprotein, CA 15–3 is a transmembrane form of the glycoprotein that is released from breast cancer cells into the blood circulation." (PMID 26890881, 2016). "In breast cancer cells we found substantial MUC1-TM expression (examples of expression in 3 breast cancer samples, left-hand panels), consistent with elevated MUC1-TM expression in breast tumors as described in the literature." (PMID 27768738, 2016). "Epithelial cells of breast cancer tissue, however, show in many instances very high MUC1-TM expression." (PMID 27768738, 2016). "While the malignant epithelial cells of pancreatic cancer show limited expression, in breast cancer tissue MUC1-ARF demonstrates strong nuclear expression." (PMID 27768738, 2016). "For instance, the epitope of MUC1 named Cancer Antigen 27-29 (CA 27-29) was used to monitor breast cancer." (PMID 27374181, 2016). "Our results demonstrate that in breast cancers containing SRCs, low MUC1 expression and/or its CM subcellular localization patterns are associated with unfavorable clinicopathological factors." (PMID 27846863, 2016). "In breast cancer cells, upregulation of GALNT6, a glycosyltrasferase that transfers a GalNAc residue to MUC1 protein, stabilizes MUC1 and plays a critical role in the proliferation and cytoskeletal regulation of breast cancer cells." (PMID 27754373, 2016). "A pilot Phase III trial of oxidized mannan-MUC1 (5 TR) in stage II breast cancer patients reported a recurrence rate of 12.5% (2 of 16) in patients receiving mannan-MUC1 vs. 60% (9 of 15) for placebo in a 15-year follow-up." (PMID 26788922, 2016). "Cytotoxic T cells (CTLs) were generated from bloods from normal post-menopausal HLA-A*0201women and breast cancer patients stimulated in vitro with allogeneic dendritic cells (DCs) pulsed with glycosylated and/or anchor-modified MUC1 peptides." (PMID 27367740, 2016). "This led us to further investigate if the CD8+ T cells from breast cancer patients possessed the ability to become cytolytic against MUC1-expressing HLA-A*0201 breast cancer cells." (PMID 27367740, 2016). "The significance of this MUC1-ARF expression in only some of the breast cancer samples is further considered in the Discussion section." (PMID 27768738, 2016).
breast carcinoma (continued). "Similar results were obtained with anti-MUC1-ARF polyclonal antisera, reacted with both DA3-MUC1 cells as well as with T47D breast cancer cells." (PMID 27768738, 2016). "For example, on ZR-75 and MDA-MB-231 breast cancer cell lines, MUC1 glycans include core 2-trisaccharides that terminate with 3-sialylated-galactose." (PMID 27754373, 2016). "It is indeed plausible that the MUC1-tolerance is circumvented in breast cancer patients which now express a different T cell repertoire than normal healthy age-matched women." (PMID 27367740, 2016). "In breast cancer, most tumors express MUC1 and MUC3, and the expression of MUC2, MUC4, MUC5AC, and MUC6 is variable or limited." (PMID 27846863, 2016). "To determine if breast cancer patients have T cell repertoires that recognize these MUC1 peptides, we screened 23 HLA-A*0201 breast cancer patients regardless of their stage, ER/PR and HER2 status with four selected peptides (P1, P3, P4, P15)." (PMID 27367740, 2016). "The cancer antigens CA 27.29 and CA 15–3, which are derived from a mucin known as MUC-1, are commonly used biomarkers for breast cancer." (PMID 26890881, 2016). "The goal of the study was to check the effect of monoclonal antibody against MUC1 with novel platinum(II) complex (Pt12) on selected aspects of apoptosis in human MDA-MB-231 breast cancer cells." (PMID 26112902, 2015). "Here, we report that C1GALT1 is overexpressed in breast cancer and its overexpression enhances malignant growth of breast cancer cells through modifying MUC1 O-glycosylation and signaling." (PMID 25762620, 2015). "MUC1 vaccine containing the cDNA (M-FP) is also tested in the third phase of clinical trial in patients with breast cancer." (PMID 26112902, 2015). "In this study, we found that overexpression of C1GALT1 decreases Tn antigens and increases T antigens on cell surfaces and MUC1 and enhances breast cancer cell malignant behaviors." (PMID 25762620, 2015). "The mechanistic investigation indicates that C1GALT1 regulates the O-glycan structures on MUC1 oncoprotein, and promotes MUC1-N shedding and MUC1-C/β-catenin signaling pathway in breast cancer cells." (PMID 25762620, 2015). "Monoclonal antibody against MUC1 increased sensitivity of breast cancer cells to the platinum(II) compound." (PMID 26112902, 2015). "Increased expression of MUC1 induces thyroid cancer cell resistance to cisplatin, docetaxel and doxorubicin and it induces the resistance to trastuzumab in breast cancer cells." (PMID 26112902, 2015). "For instance, Rudd and coworkers described an overexpression of a glycoprotein, MUC1, in patients with breast cancer." (PMID 26157795, 2015). "In our study, we proved that anti-MUC1 used in combination with Pt12 strongly induced apoptosis in MDA-MB-231 breast cancer cell line." (PMID 26112902, 2015). "Two-photon luminescence confocal and darkfield scattering imaging revealed targeting of MUC1-BSA-PD-NRs to MUC1+ MCF-7 breast cancer and SCC-15 squamous cell carcinoma cells lines." (PMID 26147830, 2015). "MUC1-BSA-PD-NRs substantially decreased cell viability in photoirradiated MCF-7 cell lines vs. MUC1- MDA-MB-231 breast cancer cells (p < 0.005)." (PMID 26147830, 2015). "High expression levels of T antigens were found on MUC1 and promoted breast cancer metastasis through galectin-3." (PMID 25762620, 2015). "MUC1 is also involved in increasing the proportion of SP cells in the breast cancer cell line MCF-7." (PMID 26016502, 2015). "Cytosolic localisation of MUC1, on the other hand, has been found to be elevated in breast cancer and to protect pancreatic cancer cells from undergoing apoptosis." (PMID 25986064, 2015). "Understanding the pathways by which Pt12 with anti-MUC1 induces cell death can provide information necessary to target-specific cell death pathways in the treatment of breast cancer." (PMID 26112902, 2015). "Mucin 1 (MUC1) is a transmembrane member of this family that was identified by its overexpression in human breast cancers." (PMID 26267657, 2015).
breast carcinoma (continued). "Consistent with this, early study showed that MUC1 promoter region contained NF-κB/p65 binding site that mediated the proinflammatory cytokines-induced MUC1 promoter activity and gene expression in normal breast epithelia and breast cancer cells." (PMID 25971429, 2015). "In another study, MUC1 siRNA in MDA-MB-468 breast cancer cell line was reported to decrease proliferation and invasion and increase stress-induced apoptosis, but MUC1 siRNA in BT-20 breast cancer cell line increased proliferation." (PMID 26367866, 2015). "Analysis of additional markers of EMT revealed that breast cancer samples with high PEAK1 levels expressed reduced levels of the epithelial markers MUC1, E-Cadherin and Entactin and increased levels of the mesenchymal markers Syndecan1 and LEF1." (PMID 26267863, 2015). "MUC1 has been shown to interact with hormone receptors e.g. by stabilizing ER and by stimulating ER-mediated transcription, hereby indicating a functional interaction of MUC1 and hormone receptor signalling in breast cancer." (PMID 25986064, 2015). "The altered glycosylation of serum MUC1 in breast cancer is another possibility for the early diagnosis of breast cancer." (PMID 26509158, 2015). "To date, vaccines against pancreatic cancer (telomerase peptides), lung cancer (MUC1), breast cancer (HER2), and prostate cancer (prostatic acid phosphatase, PAP) have been tested clinically." (PMID 25990580, 2015). "We have previously shown that the complex of CIN85 and MUC1 plays a crucial role in matrix degradation and invasion by different breast cancer cells." (PMID 25675408, 2015). "In mice, however, data are available showing that MUC1 activates cSRC signaling by influencing the association of PI3K and β-Catenin leading to a delay in mammary tumor progression." (PMID 26205886, 2015). "MUC1 is expressed in both mammary epithelial cells and mammary tumor cells, although its expression on the latter is higher." (PMID 26943450, 2015). "In fact, we have previously shown that canine mammary tumor cells invading the vasculature express MUC1 (weighting approximately 120 kDa) at focal adhesions, reinforcing its role in cell motility." (PMID 25850034, 2015). "The combined treatment Pt12 (10 μM) with anti-MUC1 (10 μg mL−1) reduced [3H]thymidine incorporation into DNA in breast cancer MCF-7 after 24 h to 21.0 % in MCF-7 cells and 22.0 % in MDA-MB-231 cells." (PMID 24639126, 2014). "Overexpression of ST3Gal1 under the human MUC1 promoter in a spontaneous murine breast cancer model resulted in significantly decreased tumor latency compared to mice without ST3Gal1 overexpression." (PMID 24592356, 2014). "In 1992, Ceriani and colleagues conducted immunohistochemistry (IHC) analysis of MUC1 cytoplasmic and membranous expression/localization on 227 breast cancer patients." (PMID 25261375, 2014). "MUC1 has also been implicated in cytoskeletal reorganization and cell motility through Src-CrkL-Rac1/Cdc42 signaling cascade following ICAM-1/MUC1 interaction in breast cancer cells." (PMID 24504508, 2014). "They found that low cytoplasmic intensity and high cell surface localization of MUC1 correlated with better prognosis of breast cancer patients and survival." (PMID 25261375, 2014). "The cellular response of human breast cancer cells to Pt12 with anti-MUC1 has been studied using cisplatin as a reference." (PMID 24639126, 2014). "Understanding the pathways by which Pt12 with anti-MUC1 induce cell death can provide information necessary to target specific cell death pathways in the treatment of breast cancer." (PMID 24639126, 2014). "Cytotoxicity of Pt12 with anti-MUC1 against breast cancer cells is due to apoptotic cell death as well as necrotic cell death." (PMID 24639126, 2014). "The incubation of MCF-7 and MDA-MB-231 breast cancer cells with Pt12, cisplatin, Pt12 with anti-MUC1, and cisplatin with anti-MUC1 induced the visible phosphatidylserine exposure after 24 and 48 h of treatment." (PMID 24639126, 2014).
breast carcinoma (continued). "Intriguingly, MUC1 post-transcriptionally stabilizes galectin-3 expression in breast cancer cells, which was attributed to MUC1 mediated suppression of microRNA-322 expression." (PMID 25261375, 2014). "Mucin 1 (MUC1) is a heterodimeric transmembrane protein that is aberrantly overexpressed in human breast cancers as a result in part of MUC1 gene amplification and dysregulation of its transcription." (PMID 24770886, 2014). "MiR-145 suppresses cell invasion and lung metastasis of breast cancer in vitro and in vivo, and this effect is, in part, attributed to silencing of MUC1 90,131,132." (PMID 25124875, 2014). "The second modality was mucin-1 (MUC1)-specific cytotoxic T lymphocytes (CTLs), generated by MUC1 stimulation of peripheral blood mononuclear cells, to target the human breast cancer cell line, MCF7." (PMID 24932299, 2014). "Pt12 with anti-MUC1 was proved to be a stronger inhibitor of collagen biosynthesis in breast cancer cells compared to Pt12 alone and cisplatin with anti-MUC1." (PMID 24639126, 2014). "In this study, the effects of Pt12 with anti-MUC1 on collagen and DNA biosynthesis in human breast cancer cells were compared to those evoked by cisplatin and cisplatin with anti-MUC1." (PMID 24639126, 2014). "The aim of the study was to evaluate the antiproliferative properties of a new dinuclear platinum(II) complex (Pt12) used with anti-MUC1 in human breast cancer cells." (PMID 24639126, 2014). "The aim of the study was to evaluate the antiproliferative properties of a new dinuclear platinum(II) complex Pt12 used together with anti-MUC1 monoclonal antibody in human breast cancer cells and human fibroblasts." (PMID 24639126, 2014). "Our results showed that Pt12 with anti-MUC1 is more effective than Pt12 alone or cisplatin with anti-MUC1 in breast cancer MCF-7 and MDA-MB-231 cells." (PMID 24639126, 2014). "The antiproliferative effect of Pt12 with anti-MUC1 was dependent on the estrogen receptor status of the breast cancer cells." (PMID 24639126, 2014). "Other studies of breast cancer cells have demonstrated that MUC1 is detectable in “side populations” that express the ABCG2 transporter, which has been used as marker of stem/progenitor cells." (PMID 24770886, 2014). "Pt12 with anti-MUC1 was more effective in decreasing the viability of human breast cancer cells compared to the therapy cisplatin with anti-MUC1." (PMID 24639126, 2014). "Clinical observation showed that increased Siglec-1 is present in splenic marginal cell lymphoma as well as in macrophage infiltrates of MUC1-positive breast cancers." (PMID 24592356, 2014). "One study has demonstrated that MUC1 expression is increased in breast cancer cells that form mammospheres; whereas, another publication reported that MUC1 is decreased under these conditions of anchorage-independent growth." (PMID 24770886, 2014). "The release of MUC1 in breast carcinoma cells and tracheobronchial epithelial cells seems to use this pathway." (PMID 24911657, 2014). "As different glycosylation was previously found on breast cancer MUC1, pancreatic RNAse1 and prostate cancer PSA, we attempted to look at the glycosylation status of CA125." (PMID 23896595, 2013). "Other mucins, such as MUC1 (breast cancer) or prostate specific antigen (PSA, prostate cancer), have been used for cancer detection and progression monitoring, however, their sensitivity and specificity are limited." (PMID 23896595, 2013). "For example, it has been shown that breast cancer cells expressing MUC1 have a poor response to chemotherapy." (PMID 23708102, 2013). "In our previous glycosylation studies on breast cancer MUC1, pancreatic cancer RNAse1 and prostate cancer PSA, we found different glycosylation in tumour origins." (PMID 23896595, 2013).